SP2 (Sp2 transcription factor)
Description:
Binds to GC box promoters elements and selectively activates mRNA synthesis from genes that contain functional recognition sites.
Synonyms: KIAA0048
Tractability: PROTAC: ubiquitination databases record sites on it; its protein half-life has been measured.
Gene: Protein-coding gene on chromosome 17 (47,896,150 to 47,928,957, forward strand). Ensembl gene ENSG00000167182.
Subcellular location: Nucleus
Subcellular location (Human Protein Atlas): Nucleoplasm; Vesicles
Gene Ontology:
Molecular function: DNA-binding transcription repressor activity, RNA polymerase II-specific; histone deacetylase binding; protein binding; RNA polymerase II cis-regulatory region sequence-specific DNA binding; sequence-specific double-stranded DNA binding; DNA-binding transcription factor activity, RNA polymerase II-specific
Biological process: negative regulation of transcription by RNA polymerase II; immune response; regulation of transcription by RNA polymerase II
Cellular component: nucleoplasm; chromatin; nucleus
Genetic constraint (gnomAD): Loss-of-function variants: 8 observed, 45.99 expected, observed/expected ratio (o/e) 0.17, 90% interval 0.1 to 0.31. The upper end of that interval is the gene's LOEUF score, 0.31, which puts it in group 1 of 6, group 1 being the genes least tolerant of losing a copy. Missense variants: 573 observed, 819.37 expected, observed/expected ratio (o/e) 0.7, 90% interval 0.65 to 0.75. Synonymous variants: 310 observed, 335.61 expected, observed/expected ratio (o/e) 0.92, 90% interval 0.84 to 1.01.
Homologues: Orthologues: chimpanzee SP2 (99% identical), pig SP2 (97% identical), macaque SP2 (96% identical), dog SP2 (94% identical), mouse Sp2 (94% identical), rat Sp2 (94% identical), rabbit SP2 (89% identical), guinea pig SP2 (89% identical), zebrafish sp2 (61% identical), tropical clawed frog sp2 (60% identical). Paralogues in human: SP4 (40% identical), SP3 (35% identical), SP1 (35% identical).
Diseases named in the same sentence as SP2 in open-access papers:
SP2 is named in the same sentence as 48 diseases in open-access papers, as found by Europe PMC text mining. Sharing a sentence is not in itself a finding about the gene and the disease. The quoted sentences say what the papers report.
myeloma (9 papers, 2010 to 2025). "spiralis antigen showed a reaction with anti- Sp2/0 myeloma cells, with tropomyosin being a significant component of myeloma-associated antigens." (PMID 40402283, 2025). "We also tested the effect of Midn deletion in Sp2/0-Ag14 (Sp2/0) hybridoma cells (a myeloma–B cell fusion)." (PMID 38625151, 2024). "We report here an interesting case of PCR-based cloning using SP primers, in which identification of the antigen-specific light chain was complicated because it was significantly (~95%) homologous to the Sp2/0 myeloma kappa chain." (PMID 34634047, 2021). "The chromosome numbers of Sp2/0 myeloma cell and spleen cell were 39 ± 1 and 66 ± 4 respectively, and the chromosome numbers of hybridoma cell 21H27 were 102 ± 4 among the replicates of the experiments." (PMID 28304351, 2017). "Most of these inhibitors showed similar cell protections at 3 μM, 30 μM, and 300 nM, suggesting possible interactions of these inhibitors at high concentrations with other off-targets in the Sp2 mouse myeloma cells." (PMID 21455295, 2011). "As Sp2/O-Ag14 myeloma cells derive from B lymphocytes, cells dedicated to antibody synthesis and secretion, one might expect a greater efficiency of these cells, allowing production of high quantities of antibody." (PMID 20967241, 2010). "As with all prior Sp2/0-derived hybridomas investigated by our group, the SP2 primer amplified the aberrant myeloma kappa chain, a well-described sequence which does not produce secreted light chain due to the presence of a key frameshift mutation." (PMID 34634047, 2021).
breast carcinoma (6 papers, 1994 to 2023). "Monoclonal antibody SP-2 to the tumour-associated antigen 90K was generated by immunisation with conditioned medium of human breast cancer cells." (PMID 8286203, 1994). "It was detected in culture media using the monoclonal antibody SP-2 from CG-5 breast cancer cell lines and has 90-kDa subunits, hence the name 90K." (PMID 23251263, 2013). "In this study, we collected breast cancer cells at 1st, 2nd, 3rd, and 4th which were numbered SP1, SP2, SP3 and SP4 in the spheroid formation experiment." (PMID 38037058, 2023). "Similarly, the top hub TFs we found in the integrated network such as SP1, SP2, TCF12, MYC, JUN and EGR2, were also well-known regulators in breast cancer." (PMID 26763900, 2015).
hepatocellular carcinoma (5 papers, 2020 to 2023). A malignant tumor that arises from hepatocytes. "For example, Sp2 knockdown in hepatocellular carcinoma cells decreases cell migration, proliferation and survival of hepatocellular carcinoma cells and this is due, in part, to decreasing the expression of the TRIB3 gene." (PMID 36982239, 2023). "More recently, Sp2 disruption was shown to promote invasion and metastasis of hepatocellular carcinoma, possibly through TRIB346." (PMID 35906355, 2022). "The abnormal levels of SP2 induce the aggressive phenotype of hepatocellular carcinoma, gastric cancer, and pancreatic cancer." (PMID 34307888, 2021). "Functional studies had shown that Sp2 knockdown not only leads to a decrease in cell proliferation and an increase in cell apoptosis, but also inhibits migration and invasion of hepatoma cells." (PMID 32160655, 2020). "The experiment discovered that the expression of TRIB3 and GRP78 in Sp2 silenced hepatoma cells decreased significantly." (PMID 32160655, 2020). "For purpose of further verify whether there was a certain degree of cell specificity in the biological function of Sp2, we additionally detected the hepatoma Huh7 cell line in vitro." (PMID 32160655, 2020). "Taken together, the effect of SCAMP1 on viral transcription is by the specific transcriptional inhibition of HBV EnhI/Xp, SP1, and SP2 promoters, rather than from a general or global effect on human hepatoma cells." (PMID 35216324, 2022). "SP2 targets TRIB3 to facilitate the migration and invasion ability of hepatocellular carcinoma." (PMID 34307888, 2021).
prostate carcinoma (5 papers, 2008 to 2024). A carcinoma that arises from epithelial cells of the prostate gland. "Evolutionary conserved transcription factor binding sites (TFBS) recognized by WT1, EGR1, SP1, SP2, AP2 and GATA1 were identified in the promoters of 24 differentially expressed prostate cancer genes from eight mammalian species." (PMID 18631392, 2008).
gastric cancer (4 papers, 2014 to 2021). A primary or metastatic malignant neoplasm involving the stomach. "SP2 is highly expressed in gastric cancer tissues, knockdown of SP2 significantly inhibits the proliferation of gastric cancer cells." (PMID 33542193, 2021). "For instance, miR-638 inhibits cell proliferation by inhibiting Sp2 in gastric cancer." (PMID 27120793, 2016). "A recent paper showed that miR-638 could inhibit cell growth by targeting Sp2 in gastric cancer." (PMID 25301729, 2014). "For instance, miR-638 binds with SP2 mRNA 3′UTR and negatively regulate SP2 expression, therefore inhibits the proliferation of gastric cancer cells." (PMID 33542193, 2021). "In addition, Zhao and his collaborators 12 have also carried out research on this, and the results confirm that there is an up‐regulation of SP2 expression in human gastric cancer tissue, miR‐638 may induce G1 phase cell cycle arrest by down‐regulating the expression of Sp2." (PMID 32160655, 2020).
glioma (3 papers, 2020 to 2022). A benign or malignant brain and spinal cord tumor that arises from glial cells (astrocytes, oligodendrocytes, ependymal cells). "The expression levels of ZHX2 and miR-651–3p were remarkedly reduced, while HNRNPD, linc00707, and specific protein 2 (SP2) expression were remarkedly increased in glioma." (PMID 36232466, 2022). "In this study, we first identified the endogenous expressions of HNRNPD, ZHX2, linc00707, miR-651-3p, and SP2 in glioma tissues and cells." (PMID 33542193, 2021). "Western blot assay was applied to measure the expression of SP2, we found that SP2 was significantly highly expressed in glioma tissues and cells." (PMID 33542193, 2021). "We found that in pre-miR-651-3p + SP2(+)-NC group, the proliferation, migration, invasion, and VM formation ability of glioma cells were significantly reduced, while they were significantly increased in pre-NC + SP2(+) group." (PMID 33542193, 2021). "Our study found that SP2 is highly expressed in glioma tissues and cells, knockdown of SP2 significantly inhibited the VM formation ability." (PMID 33542193, 2021). "It is suggested that miR-651-3p binds to the 3′UTR of SP2 mRNA and negatively regulate its expression, thereby regulates the formation of VM in glioma cells." (PMID 33542193, 2021). "Compared with pre-NC + SP2(+) group, those abilities of glioma cells were significantly reduced in the pre-miR-651-3p + SP2(+) group." (PMID 33542193, 2021). "Moreover, increasing the ZHX2 and miR-651–3p expression or decreasing the expression of HNRNPD, linc00707, and SP2 suppressed glioma cells’ proliferation, migration, invasion, and VM formation." (PMID 36232466, 2022). "The results revealed that compared with SP2(+)-NC group, glioma cells with overexpressed SP2 showed a significantly improved ability in proliferation, migration, invasion, and VM formation, while SP2(−) group was significantly reduced compared to SP2(−)-NC group." (PMID 33542193, 2021). "Meanwhile, we found that knockdown of both linc00707 and miR-651-3p could reverse the miR-651-3p repression function on its target gene SP2 and the ability of VM formation in glioma cells." (PMID 33542193, 2021). "In the present study, HNRNPD, linc00707, and specific protein 2 (SP2) were highly expressed, while zinc fingers and homeboxes 2 (ZHX2) and miR-651-3p were remarkedly downregulated in glioma tissues and cells." (PMID 33542193, 2021). "HNRNPD, linc00707, and SP2 knockdown or ZHX2 and miR-651-3p overexpression suppressed glioma cells proliferation, migration, and invasion and vasculogenic mimicry (VM) formation." (PMID 33542193, 2021). "It is indicated that SP2 can regulate the expression of MMP2, MMP9, and VE-cadherin and promote the formation of VM in glioma cells at the transcriptional level." (PMID 33542193, 2021). "Knockdown of SP2 significantly inhibited the mRNA and protein expression level of MMP2, MMP9, and VE-cadherin, thereby repressed the VM formation ability of glioma cells." (PMID 33542193, 2021). "Then, SP2 binds to the promoter regions of MMP2, MMP9, and VE-cadherin, which are VM formation-related proteins, and therefore, play a role in enhancing transcription for the regulation of glioma cell VM formation." (PMID 36232466, 2022). "In glioma cells, it has been reported that ZHX2 interacts with HNRNPD and further regulates vasculogenic mimicry (VM) formation through the linc00707/miR-651–3p/SP2 pathway." (PMID 36232466, 2022). "The transcription factor SP2 directly bound to the promoter regions of the VM formation-related proteins MMP2, MMP9, and VE-cadherin, playing a role in promoting transcription in order to regulate the VM formation ability of glioma cells." (PMID 33542193, 2021). "Meanwhile, overexpression of SP2 could reverse the negative effect of miR-651-3p on glioma cells." (PMID 33542193, 2021).
Anxiety (1 paper, 2017). Intense feelings of nervousness, tension, or panic often arise in response to interpersonal stresses. "The most significant SNP-behaviour association was between a SNP on Sp2 (rs3708840; missense mutation predicting threonine to isoleucine change, T166I) and an anxiety-related measure, time spent in the central area of the elevated plus maze test." (PMID 28145470, 2017). "We observed associations between loci on Sp2 (rs3708840) and Tph1 (rs262731280) and anxiety phenotype measures, which remained significant after multiple testing correction at q = 0.01." (PMID 28145470, 2017). "Specificity protein 2 (Sp2, rs3708840), tryptophan hydroxylase 1 (Tph1, rs262731280) and serotonin receptor 3A (Htr3a, rs50670893) were associated with activity/anxiety behaviours, and microtubule-associated protein 2 (Map2, rs13475902) was associated with cognitive performance." (PMID 28145470, 2017). "Comparing our results with the Wellcome Trust data on Northport Stock HS mice provided further support for the importance of the Sp2 region in anxiety regulation." (PMID 28145470, 2017). "Converging evidence from the association analyses in these two datasets, properties of the SNP analysed by us and brain expression of Sp2 all suggest that the gene can play an important role in anxiety regulation." (PMID 28145470, 2017).
atherosclerosis (1 paper, 2013). A disease characterized by the build-up of fatty material and calcium deposition in the arterial wall resulting in partial or complete occlusion of the arterial lumen. "Endothelial cell (EC) apoptosis is an important contributing factor in the development of atherosclerosis; therefore, study of the antiapoptotic activity of SP2 on ECs provides information related to the treatment of atherosclerosis and other cardiovascular diseases." (PMID 23671839, 2013).
diabetes (1 paper, 2025). "The AUROC values for detecting poorly controlled diabetes (compared to non-diabetic individuals) were 0.871 (0.850–0.891) internally, 0.851 (0.819–0.878) for SP2, and 0.655 (0.541–0.761) for BES." (PMID 40438493, 2025).
glioblastoma (1 paper, 2023). The most malignant astrocytic tumor (WHO grade IV). "SP-2 also inhibited angiogenesis by reducing HIF-1α and VEGF in the glioblastoma cells, suggesting that SP-2 has the potential to regulate the HIF-1α-associated pathways and to change cellular and genomic regulation." (PMID 36827114, 2023).
inflammatory bowel disease (1 paper, 2016). A spectrum of small and large bowel inflammatory diseases of unknown etiology. "SP2 may contribute to the differential expression level between B6 and C3Bir mice and was identified as innovative target for the therapy of inflammatory bowel diseases supporting the upregulation of the protective CD14 protein." (PMID 27191968, 2016).
ischemia (1 paper, 2015). A hypoperfusion of the BLOOD through an organ or tissue caused by a PATHOLOGIC CONSTRICTION or obstruction of its BLOOD VESSELS, or an absence of BLOOD CIRCULATION. "To investigate the effect of SP2 on the oxidative stress in vivo, we have used a rat myocardial I/R injury model (30-min ischemia followed by 4-h reperfusion)." (PMID 26699793, 2015).
keloid (1 paper, 2014). An irregularly shaped, elevated mark on the skin caused by deposits of excessive amounts of collagen during wound healing. "A potential mechanism for the activity of TA in keloid is its capacity to induce degradation of the Sp2 transcription factor." (PMID 25328513, 2014).
leukodystrophy (1 paper, 2022). Leukodystrophies are a group of rare, progressive, metabolic, genetic diseases that affect the brain, spinal cord and often the peripheral nerves. "SP2 is a milder PLP-associated leukodystrophy, where progressive degeneration of the axons of upper motor neurons is observed." (PMID 35829923, 2022).
liver cancer (1 paper, 2024). An epithelial or non-epithelial malignant neoplasm that arises from the liver. "By analysing ChIP-seq data for SP1, SP2, and SP5 in the liver cancer cell line HepG2 (downed from ENCODE), we found direct binding of SP1, SP2, and SP5 to the promoters of most SRTs near TSSs, which exhibited strong H3K27ac occupancy and open chromatin accessibility." (PMID 38185659, 2024).
lung carcinoma (1 paper, 2016). "rs1514846 on chromosome 5 was linked to 4 SNPs with CADD scores of over 10, it mapped among histone marks in A549 lung carcinoma cells and changed binding motifs for SP2 and Znf143." (PMID 26959888, 2016).
neuroblastoma (1 paper, 2024). Neuroblastoma (NB) is the most common solid, extracranial childhood tumor. "We then asked whether neuronal cells could internalize the αSyn that had been released from the cells, and treated SH-SY5Y human neuroblastoma cells with CM from Cos7 cells expressing sp2-αSyn." (PMID 38184623, 2024).
Obesity (1 paper, 2019). Accumulation of substantial excess body fat. "The prediction analysis showed that FTOBD‐associated variants disturb binding sites of SP1 and SP2; obesity‐associated variants, on the other hand, disturb binding sites of FOXP1, which are transcription factors highly expressed during prenatal development stages of the brain." (PMID 31033179, 2019).
oral cancer (1 paper, 2023). "SP-2 has been shown to induce autophagic cell death in oral cancer cells." (PMID 36827114, 2023).
pancreatic cancers (1 paper, 2011). "For instance, curcumin inhibited the proliferation of Panc28 and L3.6pL pancreatic cancer cells in vitro by down-regulating NF-kB-dependent gene transactivation and Sp1, Sp2 and Sp3 transcription factors, which are overexpressed in pancreatic cancers." (PMID 21859497, 2011).
Parkinson disease (1 paper, 2024). A progressive degenerative disorder of the central nervous system characterized by loss of dopamine producing neurons in the substantia nigra and the presence of Lewy bodies in the substantia nigra and locus coeruleus. "The distinctive behavior of sp2-αSyn prompted us to develop a novel mouse model of Parkinson’s disease based on enhanced αSyn secretion and cell-to-cell transmission." (PMID 38184623, 2024). "Thus, by displaying a nigral αSyn pathology, neuronal loss, neuroinflammation, and motor deficits, we conclude that sp2-αSyn induced a Parkinson’s disease-like pathology in non-transgenic wild type mice." (PMID 38184623, 2024).
primary ciliary dyskinesia (1 paper, 2022). A rare, genetically heterogeneous, primarily respiratory disorder characterized by chronic upper and lower respiratory tract disease. "Several genes (ARMC4, SP2, LRRC46, RSPH9, and ZMYND10) assigned to associations are involved in primary ciliary dyskinesia (PCD), an autosomal recessive inherited disease." (PMID 35052452, 2022).
retinitis (1 paper, 2022). Inflammation of the retina. "Notably, VVAPRTLIL (SP2) was not identified in the ocular fluid of CMV-retinitis patients." (PMID 36341392, 2022). "In contrast, only two of the three UL40 peptides, VMAPRTLIL (SP1) and VMAPRTLVL (SP3), were observed in the majority of intraocular fluid specimens from CMV-retinitis patients (in which one of the peptides was observed in each patient), and VVAPRTLIL (SP2) was not present in their ocular fluid." (PMID 36341392, 2022).
seminoma (1 paper, 2025). A radiosensitive malignant germ cell tumor found in the testis (especially undescended), and extragonadal sites (anterior mediastinum and pineal gland). "In contrast, the right and left specimens of the two synchronous bilateral seminomas (SP2 and SP4) do not cluster together, suggesting that their PGC formed after the separation into the right and left gonadal ridges occurred." (PMID 40358182, 2025).
Sepsis (1 paper, 2024). Sepsis is defined as life-threatening organ dysfunction caused by a dysregulated host response to infection. "In this manner, application of the 3-biomarker prediction model to all patients with sepsis-induced hypotension may improve generalizability and time to sub-phenotype identification to facilitate future clinical trials without misclassification of patients with SP2." (PMID 39011119, 2024).
Spinocerebellar Ataxia 17 (1 paper, 2023). "An ENCODE analysis exhibited SP2 (Sp2 transcription factor), as the top functional element related to HSP90B1, whereas DisGeNET showed Spinocerebellar Ataxia 17 as one of the top related diseases associated with it." (PMID 36766730, 2023).